NRAS (NRAS proto-oncogene, GTPase)
Diseases named in the same sentence as NRAS in open-access papers (continued):
Sharing a sentence is not in itself a finding about the gene and the disease.
tumor (continued). "All MM patients harbored a BRAF and NRAS wild-type tumor and received a median of 3 lines of prior therapies including ICIs, whereas the majority of patients with RCC received at least 3 lines of tyrosine kinase inhibitors (TKIs)." (PMID 34777395, 2021). "We currently devise therapies for mCRC patients based on symptoms, primary tumor site, previous treatments, cancer stage, molecular evaluation (BRAF, KRAS or NRAS mutations and microsatellite instability), comorbidities, and treatment goals." (PMID 33809053, 2021). "The co-activation of these pathways has frequently been found in several tumor types, including AML with NRAS mutations." (PMID 34638998, 2021). "At the genetic level, besides alterations in the β-catenin pathway, the tumor carried mutations in IDH1 and NRAS (codon 61) genes." (PMID 34205480, 2021). "Although somatic mutational changes within the BRAF, NRAS, NF-1, and KIT genes are seen to deregulate tumor biology within the melanocytes, acknowledgment of the contributory role of inherited factors is also due." (PMID 34155457, 2021). "All the patients underwent PET/CT scan before primary tumor resection, pathological samples were obtained, and the KRAS/NRAS/BRAF mutational status was evaluated." (PMID 34239564, 2021). "We observed that the MSKCC MSI-CRC cohort also included patients (64/97, 66%) with either a BRAF, NRAS, or KRAS mutation, whereas our MSI-CRC cohort was entirely composed of BRAF/NRAS/KRAS wild-type tumours." (PMID 34282766, 2021). "Altogether, the present data suggest that ablation of Yap or Taz mildly delayed Akt/NRas-driven liver tumor development in vivo, leading to decreased tumor cell proliferation." (PMID 33232824, 2021). "Hsa_circ_0001955 promotes the proliferation, invasion, and migration of HCC tumor cells through the miR-145-5p/NRAS pro-oncogene (NRAS) axis." (PMID 34540684, 2021). "These genes have been suggested to constitute CM’s CIMP; however, recent research highlights that CIMP is usually associated with an NRAS-mutant phenotype, which is more aggressive than a non-NRAS-mutant tumor." (PMID 34575678, 2021). "Based on these preliminary data, several trials combining MEK inhibitors and hydroxychloroquine in KRAS and NRAS mutant tumours have started." (PMID 34200676, 2021). "Of note, TERT mRNA expression levels were not different when considering other genetic alterations present in the tumours, such as BRAF, NRAS mutations and RET/PTC or PAX8/PPARγ rearrangements (Figure A1)." (PMID 32659948, 2020). "In bone marrow tumor DNA samples, the detection rate of BRAF V600Mx mutations was 4/83 (5%), KRAS Mx was 13/83 (16%), NRAS G12/G13 was 3/83 (4%) and NRAS Q61 was 14/83 (17%), which were approximately equivalent to those found using an NGS method." (PMID 32284750, 2020). "Although the first description in melanoma of a mutual exclusivity of NRAS and BRAF mutations, more recent studies have shown that their co‐occurrence was possible in the same tumor before treatment." (PMID 35847743, 2020). "Within these eleven studies, analysis of tumor mutational events varied from driver gene genotyping of KRAS, BRAF, and/or NRAS, to analysis of the genome-wide mutational spectrum of the tumor." (PMID 33228212, 2020). "While the KIF1B mutation is most likely benign, the NRAS mutation is a known oncogenic variant in other neoplastic diseases, and a novel finding for PPGL tumours, for which reason it became the focus of the present study." (PMID 33138083, 2020). "KRAS appears to be mutated in 22% of the overall tumour population, while the frequency of HRAS mutation is 2% and NRAS mutation is 8% according to cumulative data." (PMID 32772213, 2020).
tumor (continued). "Overexpression of ETV1, combined with oncogenic NRAS (G12D), can transform primary melanocytes and promote tumor formation in mice." (PMID 33424867, 2020). "Activating mutations of KRAS codon 12 were detected in four patients, and oncogenic mutations of NRAS (G13V) and BRAF (V600E) were each identified in one additional tumor, contributing to a prevalence of 54.4% for activating mutations of RAS pathway." (PMID 31953485, 2020). "Driver mutations most frequently acquired at relapse were those in KRAS and NRAS, detected in three and two tumours respectively." (PMID 33057009, 2020). "BRAF, NRAS, and TERT somatic mutations were evaluated in patient’s tumor tissue as part of clinical routine." (PMID 33122747, 2020). "We determined the tumor’s proto-oncogene B-Raf (BRAF) and NRAS mutational status using Sanger sequencing." (PMID 32028967, 2020). "Subsequently, the results of western blot analysis found that NRAS was observably upregulated in OS tissues when compared to paired para-tumor tissues." (PMID 32706759, 2020). "These alterations can occur in different genes considered “drivers” and can be mutually exclusive within the same tumor, such as BRAF and NRAS gene mutations." (PMID 32695793, 2020). "For further detail analysis, the agreement of cfDNA and tumor DNA of BRAF V600Mx was 76%, KRAS Mx and NRAS Q61 mutations were 100%, NRAS G12/G13 mutations was 100%." (PMID 32284750, 2020). "Others also found a correlation between serial ctDNA analysis of BRAF and NRAS status and tumor response." (PMID 32010431, 2020). "This selective MEK1/2 inhibitor is a benzoxazole compound with high potency and exhibits anti-tumor activity in BRAF- and NRAS-mutant tumor cell lines." (PMID 32092958, 2020). "Our idea is that sEVs released by tumor cells with the BRAF mutation harbor messages to avoid such “oncogene antagonism” by targeting NRAS in the recipient cells, which potentially harbor NRAS mutations." (PMID 32575666, 2020). "In order to identify possible mechanisms of resistance to anti-EGFR MoAbs in CRC, we analyzed tumor samples from 21 KRAS/NRAS/BRAF/PIK3CA wt mCRC patients enrolled in the CAPRI-GOIM clinical trial by targeted sequencing." (PMID 31226844, 2019). "In particular, KRAS and NRAS mutant tumours treated with MEK inhibitor are strongly but transiently responsive to the inhibitor and more susceptible to MAPK pathway reactivation." (PMID 31126017, 2019). "For a few variants, however, including NRAS Q22K and CDK4 R24C, and the MAFs in ctDNA, were higher or equivalent to the MAFs in tumor tissue, suggesting the subclonal expression of these mutations in the lesion sequenced." (PMID 31795494, 2019). "Detailed analysis of intrinsic-resistant tumours revealed several single-nucleotide variants in KRAS, NRAS, ERBB2, and PDGFRA, which likely confer resistance." (PMID 31653970, 2019). "Genetic analysis of the tumor was performed using a diagnostic biochip for the detection of somatic mutations in the BRAF, NRAS, KIT, GNAQ, GNA11, MAP2K1, and MAP2K2 genes, Sanger sequencing for searching germinal mutations in the CDKN2A gene." (PMID 30782194, 2019). "We chose a novel ERK1/2-selective pharmacologic inhibitor, SCH772984, which has shown cellular potency in tumor cells with BRAF, NRAS, or KRAS mutations and induces tumor regressions in xenograft models at toxicity-free doses." (PMID 31133044, 2019). "Genetic analysis of tumor tissue was performed using a diagnostic biochip (EIMB RAS, Russia) for the detection of most common somatic mutations in the BRAF, NRAS, KIT, GNAQ, GNA11, MAP2K1, and MAP2K2 genes." (PMID 30782194, 2019). "We propose that B2M testing is a useful adjunct to routine MMR testing and should be incorporated into a bowel tumour‐specific assay in conjunction with MLH1, KRAS, NRAS and BRAF status to provide an overall recurrence risk for individual patients." (PMID 31062389, 2019).
tumor (continued). "Genomic DNA was isolated from whole blood for the analysis of VEGF-A (rs2010963, 1570360, rs699947), ICAM-1 (rs5498, rs1799969) SNPs and from tumor tissue for the detection of genomic variants in KRAS, NRAS, BRAF genes." (PMID 31752122, 2019). "We specifically focused on currently available factors associated with thyroid carcinogenesis, including histology, tumor multifocality and further, the prominent performers of the MAP kinase pathway, BRAF and NRAS mutational status." (PMID 30666518, 2019). "Tumor KRAS and NRAS mutational statuses are usually assessed using polymerase chain reaction (PCR)-based assays designed for detection of major hotspot mutations." (PMID 31068650, 2019). "They found an enrichment of tumours with HER2 amplification in cetuximab‐resistant KRAS/NRAS/BRAF/PIK3CA wild‐type tumours." (PMID 31282586, 2019). "The VAF of BRAF mutations were relatively concordant with that of RAS mutations, except for one tumor with coexistence of class-2 BRAF mutation and NRAS mutation." (PMID 31277584, 2019). "Tumour samples from all patients were screened for known hotspot mutations in KRAS, BRAF and NRAS as part of routine diagnostic examination." (PMID 31395942, 2019). "Thirty-one tumors presented concomitant mutations in two genes; three tumors presented concomitant mutations in three genes including one tumor with BRAF, NRAS and PIK3CA concomitant mutations and two tumors with BRAF, KRAS, and PIK3CA concomitant mutations." (PMID 31036005, 2019). "A broad approach with a panel of genes should be relevant to detect actionable mutations in other genes than KRAS, NRAS and BRAF and discuss cases in multidisciplinary molecular tumour boards." (PMID 31265477, 2019). "BRAF and KRAS are mutually exclusive, and 1 tumour harboured a double mutation in the BRAF and NRAS genes." (PMID 30837681, 2019). "Activating oncogenic mutations in KRAS and NRAS are common in CRC, driving tumor progression and influencing efficacy of both cytotoxic and targeted therapies." (PMID 31427573, 2019). "Among the 502 submitted specimens, the only tumor carrying coexisting class-1 BRAF mutation and activating NRAS mutations was seen in a pleural effusion specimen taken 3 months after combined therapy with BRAF inhibitor and MEK inhibitor." (PMID 31277584, 2019). "When compared to the mutation status obtained with FFPE tumor samples, 14 out of 17 (82%) cases showed agreement for BRAFV600 (sensitivity 67%, and specificity 75%) and 14 out of 17(82%) for NRAS (sensitivity 40%, and specificity 100%)." (PMID 30546839, 2018). "Regarding immunohistochemistry, 12/211 of the cases demonstrated NIS in the membrane of tumor cells, those cases showed variable outcomes concerning therapy success, prognosis and all but one were wild type for BRAF, NRAS and TERTp mutations." (PMID 29298843, 2018). "In almost all resistant tumours the MAPK pathway is reactivated either via activating mutations or amplification in BRAF, MEK1/2 or NRAS or via the transcriptomic upregulation of receptor tyrosine kinases, including PDGFRß and c-MET2,16." (PMID 30237495, 2018). "In all five patients, additional MAPK-activating alterations, including NRAS and MEK2 mutations, were acquired in the matched tumours progressing on BRAF inhibitor monotherapy or BRAF/MEK inhibitor combination treatment." (PMID 30237495, 2018). "It is due to the presence of heterogenous cell populations within one patient's tumor, e.g., cell clones harboring BRAF mutations and others comprising NRAS mutations." (PMID 30237393, 2018).
tumor (continued). "The BRAFi‐resistant tumor, WM3936‐1, was derived from a BRAFV600E mutant patient who developed a subcutaneous lesion harboring de novo NRAS (Q61K) and PI3KCA (H1047Y) mutations after 9 months of treatment with the BRAFi dabrafenib." (PMID 29650805, 2018). "Overall, BRAF, NRAS, and CDKN2A were found mutated in 62.5%, 12.5% and 59% cell lines and in 47%, 16%, 12% tumor tissues, respectively." (PMID 29492214, 2018). "In vitro and in vivo functional studies revealed that RASAL2 promoted tumor progression in both KRAS/NRAS mutant and wild-type CRC cells." (PMID 30037330, 2018). "The most frequently mutated genes across all tumor types included KRAS (30 patients), PIK3CA (16 patients), BRAF (6 patients), EGFR (5 patients), NRAS (4 patients), and ERBB2 (3 patients)." (PMID 29854313, 2018). "The biomarker analysis set for predictive genomic markers (KRAS, NRAS, BRAF, or PIK3CA mutations) included 46 subjects with tumour tissue sequenced." (PMID 30425349, 2018). "Six hundred eight two (51%) patients’ tumours were assessed for BRAF and NRAS mutation status; BRAF V600 and NRAS mutations were detected in 303 (44%) and 134 (20%) tumours tested." (PMID 30010756, 2018). "The pyrosequencing analysis of tumor tissue showed that 10 out of 19 (52%) patients had a BRAF mutation, 5 out 19 (26%) harbored a NRAS mutation, and 4 out of 19 (21%) patients were WT for both BRAF and NRAS genes." (PMID 30546839, 2018). "The IDH2 (R140Q) NRAS (G13R) population shrinks to 8% of the tumor at the same relapse time point at which the triple-mutant IDH2 (R140Q) NRAS (G13R) ASXL1 (G646fs) clone expands to 64%." (PMID 30087104, 2018). "In conclusion, based on our experience we suggest considering LB for patients who have not had TB or have insufficient tissue to determine the presence of KRAS/NRAS/BRAF mutations, especially in the context of high tumor burden prior to therapy." (PMID 30705875, 2018). "The primary aim of this study was to explore if patients with BRAF or NRAS mutant tumours compared to patients with wild-type tumours have an increased risk of developing disease recurrence following a negative SLNB." (PMID 29755118, 2018). "Thirty-one cfDNA samples positive for IDH1, KRAS, PIK3CA, NRAS, AKT, BRAF, and IDH2 mutations in tumor tissue were selected for ddPCR, MassARRAY and NGS comparison." (PMID 29535804, 2018). "Most studies have employed primary tumor samples from sCRC patients to define the mutations of KRAS, NRAS, BRAF and PI3KCA genes." (PMID 30344942, 2018). "The most frequently mutated genes across all tumor types included KRAS, PIK3CA, BRAF, EGFR, NRAS and ERBB2." (PMID 29854313, 2018). "Quite identical mutation patterns between primary tumors and metastatic lesions were found for BRAF and NRAS genes; mutations of CDKN2A gene appeared to be instead selected during tumor progression." (PMID 29492214, 2018). "The risk of disease recurrence following a negative SLNB was increased for patients with either a BRAF or NRAS mutant tumour compared to wild-type tumours (aHR 1.92, 95% CI: 1.02–3.60, p = 0.04)." (PMID 29755118, 2018). "This accounted for 38/351 patients (10.8%) in the prospective cohort (37 CRC patients with activating KRAS or NRAS mutations and one GIST patient with a PDGFRA D842V mutation) and is also an important outcome of tumour testing." (PMID 28196074, 2017).
tumor (continued). "Aberrant RAS activation plays causal role in human cancer with an estimated 30% of human tumours harbouring somatic oncogenic mutations mainly in KRAS, but also in NRAS and HRAS." (PMID 28497782, 2017). "NGS-based profiling of the tumor genome identified a single nonsynonymous mutation among the many genes noted for recurrent mutations in CRC (e.g., KRAS, NRAS, BRAF, PIK3CA) and a striking focal amplification of the FGFR2 gene." (PMID 28835367, 2017). "Taken together with published work, these data suggested that tumor cells with mutant NRAS possess enhanced capability for automatic metastasis to the lungs, being thereby accompanied by myeloid cells to form metastatic niches." (PMID 28341702, 2017). "This tumor was also investigated for KRAS, NRAS, BRAF, and PIK3CA mutations, and a mutation in KRAS exon 4 was found, namely the c.351A>C, p.Lys117Asn." (PMID 29072370, 2017). "Among CRC patients with mutated RAS tumours (37/88; 42.0%), four tumours would have been classed as wild-type RAS using conventional diagnostics: two had NRAS codon 61 mutations and two had KRAS codon 146 mutations (outside the scope of the cobas assay)." (PMID 28196074, 2017). "NRAS‐mutation(+) CRC significantly correlated with older age, distal colon, more mucinous component of the tumor, and lower lymph vessel invasion when compared with KRAS‐mutation(+) CRC." (PMID 28378457, 2017). "Interleukin‐8‐related chemokines were identified as the tumor cell‐secreted culprits for NRAS‐dependent pulmonary metastatic propensity, signaling to lung endothelial and myeloid cells to facilitate pulmonary invasion." (PMID 28341702, 2017). "NRAS p.Q61R is a well-known oncogenic substitution previously reported in > 1300 tumor samples (COSMIC) including skin, thyroid, large intestine and hematological malignancies." (PMID 28542371, 2017). "Here, we describe how NRAS gain of function promotes lung metastasis in mice by facilitating pulmonary homing of circulating tumor cells." (PMID 28341702, 2017). "NRAS‐driven chemokine signaling by lung‐extravasated tumor cells is likely responsible for the homing of myeloid cells to the lungs in our models." (PMID 28341702, 2017). "In this study using the subset of TCGA-SKCM samples filtered by estimated tumor purity, BRAF and NRAS mutations were found to occur in a mutually exclusive pattern." (PMID 29383127, 2017). "Associations with clinical features, characteristics of the primary culprit tumor, and progression and survival data were assessed based on the mutation status of BRAF and NRAS, revealing the three cohorts BRAF-mutant, NRAS-mutant and WT." (PMID 28797232, 2017). "Mice inoculated with NRAS mutant SK-Mel147 cells were treated with G9, PD or their combination, and tumour growth was assessed over a 3-week treatment interval." (PMID 28198367, 2017). "A high intra-tumor copy number variation of NRAS/chromosome 1 was observed in 25% (8/32) of BRAF/NRAS WT, 30% (9/30) of HET and 23.8% (5/21) of High non-HET." (PMID 28668077, 2017). "Similar to other known paracrine molecular targets of RAS that have been shown to foster extravasation, we show that NRAS impacts tumor cell homing to the lungs likely via CXCR1/2 signaling." (PMID 28341702, 2017). "FISH revealed that chromosome 1 instability was the predominant mechanism of M%NRAS increase, with chromosome 1 polysomy observed in 28.6% of cases and intra-tumor cellular heterogeneity with copy number variations of chromosome 1/NRAS in 23.8%." (PMID 28668077, 2017). "In 23.1% of samples (24/101), we observed intra-tumor cellular heterogeneity in NRAS/chromosome 1 copy numbers." (PMID 28668077, 2017).